HCG22 (HLA complex group 22)
Synonyms: PBMUCL2; FLJ37114
Gene: Long non-coding RNA gene on chromosome 6 (31,053,311 to 31,065,229, forward strand). Ensembl gene ENSG00000228789.
Subcellular location: Secreted
Diseases named in the same sentence as HCG22 in open-access papers:
HCG22 is named in the same sentence as 13 diseases in open-access papers, as found by Europe PMC text mining. Sharing a sentence is not in itself a finding about the gene and the disease. The quoted sentences say what the papers report.
oral cancer (4 papers, 2017 to 2020). "Consistent with another previous study, we identified that the low expression level of lncRNA HCG22 was associated with poor survival in oral cancer." (PMID 32571304, 2020). "HCG22 expression levels have been reported to be down-regulated in oral cancer and its low expression was associated with poor survival in a recent study based on TCGA data analysis." (PMID 31827401, 2019). "HCG22 was found to be down-regulated in oral cancer and its lower expression was reported to be associated with poor survival in a recent lncRNA study using TCGA data." (PMID 28415559, 2017). "Additionally, we found lncRNA HCG22 exhibiting superior potential as a diagnostic and prognostic marker of oral cancer." (PMID 32571304, 2020). "Importantly, these results provided us with important information regarding the diagnostic and prognostic role of lncRNAs in oral cancer and pointed out lncRNA HCG22 as a candidate prognosis biomarker or potential therapeutic target." (PMID 32571304, 2020). "Based on the HCG22-associated subnetwork, we proposed that HCG22 might be an essential regulator in oral cancer by being a sponge for miRNAs." (PMID 32571304, 2020). "Several miRNAs competed by HCG22 and mRNAs were associated with oral cancer." (PMID 32571304, 2020). "We found that HCG22 was positively correlated with overall survival and considered HCG22 as a key lncRNA responsible for the prognosis of oral cancer." (PMID 32571304, 2020). "HCG22 (HLA complex group 22) is a long non-coding RNA gene that has been found to be down-regulated in oral cancer recently." (PMID 32571304, 2020). "HOTTIP and HCG22 can interact with hsa-mir-21 in the ceRNA network, which promote oral cancer invasion via the Wnt/β-catenin pathway." (PMID 31681590, 2019). "In summary, HCG22 may have the potential to become a novel biomarker for the detection and diagnosis of oral cancer." (PMID 32571304, 2020). "Therefore, we supposed that HCG22 may play a more significant role in the pathogenesis and prognosis of oral cancer." (PMID 32571304, 2020). "However, there is no experimental evidence to support the contribution of HCG22 to the development of oral cancer." (PMID 32571304, 2020).
bladder cancer (2 papers, 2020 to 2023). "Low-expression of HCG22 has been confirmed to be associated with several types of diseases, including esophageal squamous cell carcinoma, bladder cancer, and steroid-induced ocular hypertension." (PMID 32571304, 2020). "HCG22 prevents the proliferation and metastasis of bladder cancer cells by controlling PTBP1." (PMID 36602530, 2023).
laryngeal squamous cell carcinoma (2 papers, 2022 to 2024). A squamous cell carcinoma that arises from the larynx. "Besides, the interaction pairs of HCG22/EGOT-hsa-miR-1275-FAM107A and HCG22/EGOT-hsa-miR-1246-Glycerol-3-phosphate dehydrogenase 1 are likely to have a significant role in laryngeal squamous cell carcinoma." (PMID 38609844, 2024).
dilated cardiomyopathy (1 paper, 2016). Cardiomyopathy which is characterized by dilation and contractile dysfunction of the left and right ventricles. "The locus at chromosome 5q31 carrying the non-coding steroid receptor RNA activator (SRA1) as well as human leukocyte antigen (HLA) complex group 22 (HCG22) at chromosome 6p21 have been significantly associated with dilated cardiomyopathy (DCM)." (PMID 27049585, 2016).
oral squamous cell carcinoma (1 paper, 2022). "For example, the HCG22 hub inhibited cell proliferation and invasion and induced apoptosis in oral squamous cell carcinoma (OSCC) cells." (PMID 35525925, 2022).
vitiligo (1 paper, 2021). Generalized well circumscribed patches of leukoderma that are generally distributed over symmetric body locations and is due to autoimmune destruction of melanocytes. "There is no report that vitiligo is associated with either HCG22 or C6orf15, but interestingly, rs9263871 within the class I region (C6orf15-HCG22) has been shown to have the strongest evidence of an association with LN." (PMID 35082778, 2021).
tumor (3 papers, 2019 to 2025). "HCG22 was negatively associated with tumor stage in our study." (PMID 30755833, 2019). "The model includes PRKCQ, FUOM, H2BC21, LAMTOR4, and HCG22, along with critical clinical factors such as age, tumor grade, and tumor stage (T and N)." (PMID 40817807, 2025).
cancer (2 papers, 2019 to 2022). A tumor composed of atypical neoplastic, often pleomorphic cells that invade other tissues. "In addition, bioinformatics analysis confirmed that HCG22 is differentially expressed in various cancers, and the mechanism in OSCC should be researched." (PMID 31681590, 2019). "Totally, we obtain 28 research in PubMed that introduce HCG22 as a key lncRNA in diverse cancers, but none of them were investigated on STAD." (PMID 35525925, 2022).
HCG22 also shares sentences with these, for which no sentence is quoted: dementia (1 paper); esophageal squamous cell carcinoma (1); gastrointestinal tumours (1); myocardial infarction (1); oropharyngeal squamous cell carcinoma (1).